STAT3 (signal transducer and activator of transcription 3)
Diseases named in the same sentence as STAT3 in open-access papers (continued):
Sharing a sentence is not in itself a finding about the gene and the disease.
infection (continued). "IL-6, a cytokine significantly elevated in DENV-infected AG129 mice and associated with disease in humans is an activator of STAT3 and thus this is a pathway unique in the mouse that may induce FB during DENV-infection." (PMID 33410734, 2021). "Coxiella burnetii induces expression of STAT3 and IL-10 during murine infection." (PMID 33789347, 2021). "Further, B cell-specific deficiency of STAT3, while leading to profound attenuation of MHV68 peak latent splenic reservoir following intranasal inoculation, presents with a significantly more modest viral phenotype following intraperitoneal infection." (PMID 33824206, 2021). "Importantly, interleukin 6 (IL6), the primary inducer of STAT3-mediated hepcidin synthesis was significantly increased in the liver of WT-infected mice as compared to ΔspvB-infected mice at 3 days post-infection." (PMID 33475464, 2021). "Despite the role of STAT3 in T-cell functions, STAT3 and its downstream innate pathways have not been well-defined in fast immunity and protective mechanisms in human TB and other infections." (PMID 34307193, 2021). "Moreover, the overexpression of pSTAT3 and STAT3 at day 3 post-infection was observed mainly in HMECs infected with HCMV-DB, but to a lesser extent with HCMV-TB40/E." (PMID 35003089, 2021). "Moreover, several transcriptomic studies have identified STAT3 among the top DEGs in response to infection with agents of BRDC, indicating its important role during BRD." (PMID 34733317, 2021). "In our study, only infection in old RMs caused an increase in the proportion of IL-6-secreting cells in lung tissue, accompanied by an increase in the activation level of NF-κB in ACE2+ cells, and enhanced STAT3 and NF-κB activation in ACE2- cells." (PMID 34471088, 2021). "Thus, these IL-4 regulatory mechanisms, particularly the role of STAT3, warrants further investigation in the context of infection/vaccination." (PMID 34006897, 2021). "Interestingly, the signal transducer and activator of transcription 3 (STAT3) pathway seems to be activated during infection with BKPyV, for example phosphorylated STAT3 is significantly (P < 0.0001) elevated on day 6 following infection." (PMID 32588533, 2020). "Moreover, several TFs, such as NFKB1, p65, JUN, SP1 and STAT3, were demonstrated previously to be involved in the regulation of lung inflammation and immunity during pathogen infection or external stimulation." (PMID 32592597, 2020). "Interestingly, we were able to confirm our results regarding the STAT3 pathway involvement during BKPyV infection and we identified IL‐11 as interesting therapeutic target, since it was significantly elevated during infection." (PMID 32588533, 2020). "This would predict that cytokines that signal through STAT3 could shift the hybrid population over the course of infection." (PMID 32634740, 2020). "Interestingly, another study published several years ago investigated the function of STAT3 in VACV-ACAM2000 infection, and the results suggested a defensive role of STAT3 in VACV infection." (PMID 32708182, 2020). "Activation of STAT3 is mediated by JAK2 upon KSHV de novo infection." (PMID 33182552, 2020). "Infection of WT, GSK3α−/−, or GSK3β−/− cells with WT Salmonella resulted in a similar amount of Y705-phosphorylated STAT3, which was no longer detected in lysates from GSK3α/β−/− cells, despite similar total STAT3 levels." (PMID 31862381, 2020). "Furthermore, many NF-κB and STAT3 target genes induced during HTLV-1 de novo infection are critical for HTLV-1-mediated dysregulation of host type I Interferon antiviral signaling." (PMID 33182552, 2020). "Therefore, we suggest that the abrogation of STATs activity by HBx to attenuate the interferon-mediated suppression of infection depends on STAT1 instead of STAT3." (PMID 32878239, 2020). "It has been shown that KSHV de novo infection rapidly induces STAT3 phosphorylation at Y705." (PMID 33182552, 2020).
infection (continued). "In contrast, our observations here indicate that NK cell-intrinsic deficiencies for Stat3, Il15ra, or Il10r1 do not impact systemic IFNγ production or Lm bacterial burdens at 24 h post-infection." (PMID 31552035, 2019). "We also noted that STAT3 might play a central role in the interplay of IL-17 and IL-10 during infection and it may be a new target for the therapy of PCP in the future." (PMID 31582901, 2019). "Moreover, the expression of several proinflammatory factors, including TNFα, IL-1β, and IL-8, is also mediated by Ec-STAT3 during infection." (PMID 31293595, 2019). "In wild-type mice lacking the Cre allele, there was significant protection against challenge, but in myeloid-specific STAT3-deleted animals, parasite loads were similar in primary and secondary infection, showing a failure of protective immunity in the STAT3-deficient setting." (PMID 31708913, 2019). "The upregulation of PIAS3 and SOCS1 and the significant degradation of unSTAT3 at the later stage of infection may partially explain the reduced expression of STAT3 target genes in the late stage of EV71 infection." (PMID 31575039, 2019). "The STAT3 targets that increased in the early infection were mainly inflammatory regulators including pro-inflammatory factors IL1B, IL6 and immunosuppressive factor IL10, which might contribute to the immune regulatory role of glia in CNS during infection." (PMID 31575039, 2019). "Mice lacking STAT3 in their myeloid compartment were found to phenocopy the MIF-deficient mice in failing to reject a challenge infection of H. polygyrus." (PMID 31708913, 2019). "Thus, while the role of STAT3 in T cells in the control of M. tuberculosis remains to be studied, these results illustrate the pleiotropic effect of STAT3 in regulation of infection-induced immune responses in different cell types." (PMID 29338039, 2018). "Similarly, at 24h post infection the levels of lung phospho-STAT3 (pSTAT3) are greater (3.6 fold) in WT mice than in NKLAM-KO mice." (PMID 29518136, 2018). "HCV requires STAT3 and therefore promotes STAT3 signaling to maintain infection." (PMID 29543893, 2018). "Similarly, ZIKA virus (ZIKV) infection induces pY705 in primary retinal glial cells and favors the activity of the IL-6/STAT3 pathway in blood mononuclear cells from infected rhesus monkeys, albeit without any known molecular mechanism." (PMID 29543893, 2018). "Furthermore, we reveal a positive feedback loop between Notch signaling and Janus kinase (JAK)/STAT3 pathway during in vitro infection that involves Notch-boosted IL-6." (PMID 30042932, 2018). "We propose myeloid-lineage cells infiltrating the cornea tissue in response to infection are part of a local response that triggers an elevation of inflammatory cytokines and downstream activation of the gp130/STAT3 pathway to mediate corneal nerve degeneration." (PMID 28903153, 2017). "STAT3 was overexpressed in WT mouse lung and AECs-II by Ad-STAT3 infection." (PMID 28903389, 2017). "Therefore, to corroborate the implication of STAT-3, the tyrosine-phosphorylation level of this transcription factor at Tyrosine705 was investigated after infection and activation of HGEC." (PMID 28748038, 2017). "Lower STAT3 phosphorylation was noted at 1 h post-infection with Δrop16 T. gondii." (PMID 29036202, 2017). "We could speculate that the primary infection with a mixed genotype I/II strain, characterized by a high acute virulence and long-term STAT3 and STAT6 activation, partially modulates the immune response upon the challenge with genotype II strain." (PMID 28642841, 2017). "In addition and also consistent with previous observations, S. Typhimurium infected cells, particularly later in infection, showed potent activation of STAT3 as monitored by the phosphorylation of STAT3Y705." (PMID 28742135, 2017).
infection (continued). "Since the effects of filaggrin-directed siRNA appeared congruent with effects of STAT3 inhibition in the same infection system, we evaluated whether filaggrin might intersect with STAT3 signaling in infected keratinocytes." (PMID 28081250, 2017). "Similarly, esat-6 deletion mutant induced less STAT3 phosphorylation in macrophages than both wild type and esat-6 complemented strains at 1 (70%), 2 (33.5%) and 4 h (26.2%) post infection." (PMID 28106119, 2017). "The Western blot data showed that IAV-infection could activate STAT3 in early stage (15 min after addition of virus) followed by another activation at 2 h.p.i.." (PMID 26732368, 2016). "The latency defect in STAT3-null B cells was sustained for up to 8 weeks after infection." (PMID 27486189, 2016). "Importantly, the functional consequences of STAT3 activation during the early phase appear to be distinct from activation at later times after infection." (PMID 27458446, 2016). "However, the mechanism by which STAT3 modulates macrophage response, at the early stage of the infection, is still incomplete." (PMID 27384401, 2016). "In these conditions, expression of STAT3 and PY-STAT3 upon infection was fully abrogated." (PMID 27384401, 2016). "Importantly, infection-induced STAT-3 phosphorylation and Bcl-2 increase declined when cells were challenged with parasites in IL-13R downregulated conditions or in the presence of AG490." (PMID 27826299, 2016). "As expected, stable infection experiments showed RPS27a-shRNA could significantly down-regulate RPS27a expression in K562 -STAT3 cells in mRNA and protein levels." (PMID 26942564, 2016). "MHV68 targets transitional B cells and marginal-zone B cells (89, –, 91), and STAT3 might play a critical role in the infection of these subsets prior to germinal center entry." (PMID 27486189, 2016). "We investigated the level of RPS27a, p-STAT3 and STAT3 after infection with pcDNA3.1-STAT3." (PMID 26942564, 2016). "However, H5N1/483 infection led to more activation of STAT3 than H1N1/54 did and there was a decrease of activated STAT3 with time in H5N1/483 infected cells." (PMID 27344974, 2016). "The STAT3 –dependent repression of G-CSF release by macrophages suggests that STAT3 limits early migration of neutrophils at the infection site supporting that STAT3 may be essential for the coordination of innate and adaptive immune responses." (PMID 27384401, 2016). "As expected, stable infection experiments showed RPS27a, p-STAT3 and STAT3 could be significantly up-regulated in K562-STAT3 cells in mRNA and protein levels, compared with those of K562-con cells." (PMID 26942564, 2016). "While the role of STAT3 was established in TB immune response, there is little information regarding its implication in the intracellular adaptation of the bacteria during the first hours following human macrophage infection." (PMID 27384401, 2016). "We found that MHV68 requires STAT3 to establish latency irrespective of the route of infection and that this intrinsic requirement for STAT3 is not linked to dysfunction in T cell-dependent B cell processes." (PMID 27486189, 2016). "Complete deletion of STAT3 was observed 120 h post AdCre infection in vitro." (PMID 25734337, 2015). "HCMV 72-kDa immediate-early 1 (IE1) protein associates with STAT3 and rapidly promotes nuclear localization of STAT3 in the absence of robust phosphorylation at Y705 and inhibition of STAT3 nuclear localization or STAT3 expression during infection results in diminished HCMV genome replication." (PMID 26199948, 2015). "Meanwhile, STAT3 was phosphorylated only in the Hep-dG infection group." (PMID 26217322, 2015). "Defining a protective role of STAT3 in the response to infection might therefore lead to the development of novel countermeasures against vaccinia and other pathogens." (PMID 25419841, 2014).
infection (continued). "However, impairment of the APR, which is recapitulated in IL-6, gp130, and RelA/STAT3 knockout mice, also exhibit worse outcomes in response to infection." (PMID 24732911, 2014). "To elucidate whether infection of virulence H. pylori trigers the STAT3 activation in GC cells in vitro, we co-cultured the GC cell lines AGS with CagA+ H. pylori strain and CagA-H." (PMID 25594045, 2014). "Furthermore, infection of CLL cells with lentiviral STAT3-small hairpin RNA (shRNA) reduced the expression of several STAT3-regulated survival and proliferation genes and induced apoptosis." (PMID 24520283, 2014). "However, we note that although ROP16 plays a role in maintaining STAT3 activation in infected cells, there is a substantial ROP16-independent STAT3 phosphorylation response during early infection." (PMID 23527309, 2013). "We thus asked whether STAT3 activation would reduce type I interferon signaling in the context of an oHSV infection." (PMID 23936533, 2013). "The finding that endothelial activation demonstrated as increased vascular cell adhesion molecule (VCAM) expression level on endothelial cells in cardiac tissue of STAT3 KO mice is increased accommodates with the unchanged number of infiltrated Mac3+ cells found 28 days after infection." (PMID 22675647, 2012). "Whereas, the increased ANF expression level remained unchanged in STAT3 KO mice (9.37 ± 2.62 fold, P = 0.0476) and revealed a significant higher expression (P = 0.0160) of ANF in cardiac tissue of infected STAT3 KO mice compared to infected WT 28 days after infection." (PMID 22675647, 2012). "In the acute phase, an increased expression of TIMP1, which is an endogenous inhibitor of the ECM-degrading matrix metalloproteinases, prevents collagen degradation and thus revealed matrix deposition in both wild-type and STAT3 KO mice 10 days after infection." (PMID 22675647, 2012). "Early in infection, downstream signalling machinery, most notably IL-6 binding receptor subunit alpha (Il6ra) and intracellular signal transducer and activator of transcription 3 (Stat3), were upregulated, with peak upregulation observed at day 2 pi." (PMID 22679491, 2012). "Interestingly, reduced MMP13 expression found in infected STAT3 KO mice 28 days after infection is consistent with the increased collagen I protein content in infected STAT3 KO mice 28 days after infection." (PMID 22675647, 2012). "Adv-Stat3(-) amplified in MSCs and were released 4 days after infection." (PMID 22054049, 2011). "Interestingly, mouse microarray data showed Jak2, Stat1 and Stat3 as vital proteins in this pathway and were up-regulated at the 4 days post-infection." (PMID 21172007, 2010). "Given that TRP75 interacts with STAT3 during infection and itself is tyrosine phosphorylated, TRP75 may serve as an adaptor which spatially associates STAT3 with host kinases to facilitate STAT3 phosphorylation in a mechanism like those reported in S. typhimurium and B. henselae." (PMID 41115066, 2025). "SarA signaling through STAT3 drives M2 macrophage polarization during systemic Salmonella Typhimurium infection, while IL-10 secreted by T and B cells is required for dissemination of Salmonella Typhimurium from the gut to systemic sites of infection in a mouse model." (PMID 40188438, 2025). "Furthermore, HCMV-DB infection activates the signal transducer and activator of transcription 3 (STAT3) in HMECs, leading to the upregulation of cyclin-D1, a critical regulator of cell proliferation, and a marked increase in Ki-67 protein expression in infected cells." (PMID 40001942, 2025). "Interestingly, the differences in the balance between STAT1 and STAT3 involvement were also apparent ex vivo as we observed an age-dependent gradual decline in the ratio of STAT1/STAT3 transcription for infection-induced (expanded) CD4+ T cells as well as B cell populations." (PMID 40834853, 2025).
infection (continued). "For example, although STAT3 modulates cleavage of caspase 3 during infection, the apoptotic pressure elicited by STAT3 inhibition may be insufficient to outweigh the effect of XIAP stabilization, which acts downstream of other anti-apoptotic mechanisms, such as BCL-2 family proteins." (PMID 41115066, 2025). "In addition, F. novicida infection tended to enhance activation of STAT3 just after infection." (PMID 39255287, 2024). "Furthermore, activation of STAT3 signal pathway suppressed the infection of TGEV." (PMID 38438836, 2024). "Thus, considering that NF-kB and STAT3 are phosphorylated in a time-dependent manner and taking into account that the phosphorylation of both transcription factors peaks after 60–120 min, the cells were analyzed using western blotting at 2 h post infection." (PMID 38612423, 2024). "However, we also found evidence of STAT3 modulation at the post-fusion step of infection." (PMID 37830871, 2023). "We then further investigated whether TFRC affected STAT3 expression in cardiomyocytes, and found that overexpression of TFRC in cardiomyocytes by AAV9‐flag‐TFRC infection significantly increased STAT3 and phosphroylated STAT3 (p‐STAT3) expression, and Ccl2 mRNA expression." (PMID 37647427, 2023). "The IL-6/STAT3 axis is heavily involved in the pathogenic process of SARS-CoV-2 infection, and some researchers suggest that modulation of this pathway could be an important target for pharmacological therapy against the infection." (PMID 36834984, 2023). "Under chronic damage and infection, inflammatory response is activated to produce pro-inflammatory cytokines or inflammation-related genes through transcription factors such as nuclear factor-κB (NF-κB) and signal transducer and activator of transcription 3 (STAT3)." (PMID 35955552, 2022). "Of note, in the context of C. rodentium infection, STAT3 was described as an essential player for the intestinal epithelium to restrict infection by suppressing cell death to maintain intestinal integrity, which might be an alternative hypothesis for reduced STAT1 phosphorylation." (PMID 34497340, 2022). "Previously, we have shown that STAT-3 levels were significantly increased after 4 h of post-oxidative stress due to ozone exposure in male AMs from mice expressing the human SP-A2 (1A0) transgene or after 4 h following infection in mice expressing the human SP-A (1A0) or both human SP-A transgenes." (PMID 35844510, 2022). "Moreover, this crosstalk was limited only to infection as inhibition of p38MAPK in senescent HeLa cells did not cause a change in ERK or STAT3 phosphorylation and STAT3 inhibition did not alter p-ERK levels per se." (PMID 34746026, 2021). "ERS can trigger STAT3 in the acute-phase response of infection, which may then facilitate the processing and delivery of newly synthesized loads of acute-phase proteins, and thus prevent liver from injury during infection." (PMID 34335747, 2021). "As STAT3 inhibition can be immunosuppressive, this may create a situation similar to that in aging immune systems in which the ability to control infection by adaptive immunity is limited and there is subsequent compensation for this deficiency with increased inflammation." (PMID 34504808, 2021). "We conducted an explorative experimental study to prove our concept of involvement of STAT3 pathway in BKPyV infection in a 3D organotypic cell culture of urothelium and to identify interleukins which might be involved in this infection and which might be used as therapeutic targets." (PMID 32588533, 2020). "Consequently, we were raising the question which inflammatory interleukins could be involved in this activation of STAT3 pathway during infection with BKPyV, since interleukins are interesting targets for drug development." (PMID 32588533, 2020). "However, the host factors and the mechanisms required for rapid NF-κB and STAT3 activation during de novo infection and latency by these viruses are largely unknown." (PMID 33182552, 2020).